RPS6KL1 (ribosomal protein S6 kinase like 1)
Synonyms: MGC11287; RSKL2
Tractability: Small molecule: it belongs to a druggable protein family.
Gene: Protein-coding gene on chromosome 14 (74,903,951 to 74,923,302, reverse strand). Ensembl gene ENSG00000198208.
Subcellular location (Human Protein Atlas): Nucleoplasm; Cytosol
Gene Ontology:
Molecular function: protein binding; protein kinase activity; ATP binding
Genetic constraint (gnomAD): Loss-of-function variants: 41 observed, 54.38 expected, observed/expected ratio (o/e) 0.75, 90% interval 0.59 to 0.98. The upper end of that interval is the gene's LOEUF score, 0.98, which puts it in group 4 of 6, group 1 being the genes least tolerant of losing a copy. Missense variants: 697 observed, 717.02 expected, observed/expected ratio (o/e) 0.97, 90% interval 0.91 to 1.03. Synonymous variants: 287 observed, 308.11 expected, observed/expected ratio (o/e) 0.93, 90% interval 0.85 to 1.03.
Homologues: Orthologues: chimpanzee RPS6KL1 (99% identical), macaque RPS6KL1 (97% identical), pig RPS6KL1 (81% identical), dog RPS6KL1 (81% identical), rabbit RPS6KL1 (81% identical), guinea pig RPS6KL1 (79% identical), mouse Rps6kl1 (79% identical), rat Rps6kl1 (77% identical), zebrafish rps6kl1 (42% identical), tropical clawed frog rps6kl1 (39% identical), Drosophila melanogaster CG7156 (26% identical), Caenorhabditis elegans rskd-1 (22% identical). Paralogues in human: RPS6KC1 (36% identical), SNX15 (8% identical).
Diseases named in the same sentence as RPS6KL1 in open-access papers:
RPS6KL1 is named in the same sentence as 10 diseases in open-access papers, as found by Europe PMC text mining. Sharing a sentence is not in itself a finding about the gene and the disease. The quoted sentences say what the papers report.
colorectal cancer (1 paper, 2019). A primary or metastatic malignant neoplasm that affects the colon or rectum. "RPS6KL1 (ribosomal protein S6 kinase-like 1) mutation hot spots were confirmed and validated in colorectal cancers with microsatellite instability, which might be used to develop personalized tumor profiling and therapy." (PMID 31886214, 2019).
coronary artery disease (1 paper, 2025). "In general, RPS6KL1 controls cell survival and apoptosis, but has also been implicated in the cytokine network regulation of chronic inflammatory states, such as coronary artery disease." (PMID 41306196, 2025).
malaria (1 paper, 2018). Malaria is a serious and sometimes fatal disease caused by a parasite that commonly infects a certain type of mosquito which feeds on humans. "Likewise, although significant associations were seen between severe malaria and polymorphisms in seven additional genes (IL10, LPHN2 [ADGRL2], LOC727982, ARL14, RPS6KL1, CAND1, and GNAS), without further data their potential for translation remains elusive." (PMID 30033078, 2018).
adenocarcinoma (1 paper, 2019). A common cancer characterized by the presence of malignant glandular cells. "The expression levels of RRAGB, RSPH9, RPS6KL1, RXFP1, and RTL1 mRNA were significantly lower and the RRM2 mRNA level was significantly higher in the high-risk group than those in the low-risk group in NSCLC adenocarcinoma of GSE11969." (PMID 31886214, 2019). "This signature and the genes RRAGB, RSPH9, RPS6KL1, RXFP1, RRM2, and RTL1 included in this model are independent biomarkers for prediction of overall survival of NSCLC adenocarcinoma." (PMID 31886214, 2019). "Our six-gene prognostic signature for NSCLC adenocarcinoma include RRAGB, RSPH9, RPS6KL1, RXFP1, RRM2, and RTL1 genes which are not contained in the previous gene signatures." (PMID 31886214, 2019).
cancer (1 paper, 2019). A tumor composed of atypical neoplastic, often pleomorphic cells that invade other tissues. "The model signature genes RSPH9, RPS6KL1, RXFP1, and RTL1 have been revealed to be involved in cancer activity." (PMID 31886214, 2019).
RPS6KL1 also shares sentences with these, for which no sentence is quoted: breast carcinoma (1 paper); depression (1); lung adenocarcinoma (1); Stroke (1); tumor (1).